NOTCH4 (notch receptor 4)
Diseases named in the same sentence as NOTCH4 in open-access papers (continued):
Sharing a sentence is not in itself a finding about the gene and the disease.
melanoma (continued). "Based on the pan-cancer study and our specific NRAS wildtype melanoma research, we believe that NOTCH4 can be a promising ICI biomarker and is worthy of clinical verification." (PMID 35967450, 2022). "More prospective studies are urgent to determine the efficiency of NOTCH4 in NRAS widetype melanoma." (PMID 35967450, 2022). "Constitutive expression of Notch-4 in melanoma induces the transition to epithelial-like morphology cells with highly reduced migratory and proliferative activity; thus, decrease in NOTCH4 expression promotes tumor progression and forces metastasis." (PMID 34337053, 2021). "In melanoma, HR was < 1 and the median OS of NOTCH4-MUT patients (median OS: 34.8 months) was longer than that of NOTCH4-WT patients (median OS: 22.1 months)." (PMID 34284787, 2021). "For cancer types with greater than 50 samples in the discovery cohort, including NSCLC (n = 296) and melanoma (n = 287), we found that in these cancer types, compared with NOTCH4-WT patients, NOTCH4-MUT patients had a good prognosis trend." (PMID 34284787, 2021). "In keeping with this concept, several proteins that play a key role in embryogenesis, such as Nodal and Notch4, can be re-expressed in aggressive melanoma and play a functional role in the VM process." (PMID 27340778, 2016). "Studies have also shown Notch4 activity regulating Nodal function during development as well as expression in melanoma cells." (PMID 27011171, 2016). "Notch4’s regulation of lymphangiogenesis may enhance the ability of tumors to escape immune surveillance, thus affecting treatment outcomes in melanoma." (PMID 39897423, 2025). "In this place, it is worth noting the role of Notch4 in melanoma." (PMID 37108670, 2023). "Moreover, NOTCH4-Mut melanoma had a superior clinical response in the discovery cohort (ORR, 40.0% vs 13.11%, P = 0.057) and validation cohort (ORR, 68.75% vs 30.07%, P = 0.004)." (PMID 35967450, 2022). "NOTCH4 mutation may promote tumor immunity and serve as a biomarker to predict good immune response in NRAS wildtype melanoma and guide immunotherapeutic responsiveness." (PMID 35967450, 2022). "Hardy and colleagues discovered that among the family of Notch genes, Notch4 is specifically required for the expression of Nodal in aggressive melanoma cancer cells and may be an upstream regulator of Nodal." (PMID 36970723, 2022). "Upregulation of Nodal by Notch4 promoted VM formation in an aggressive melanoma cell line, MV3." (PMID 27034014, 2017). "Nevertheless, there are evidences supporting a positive relationship between Notch and VM: Notch-4 was shown to be highly expressed in several aggressive melanoma cell lines capable of VM, where it seemed to play a crucial role in the up-regulation of Nodal expression as well." (PMID 28320399, 2017). "It has been also shown that Notch4 promotes invasion and metastasis in melanoma stem-like cells." (PMID 28137308, 2017). "Additionally, previous studies reported that other genes are frequently mutated in melanoma and other cancer types, including BRCA2 (9/112, 8%), LRP1B (9/112, 8%), MET (8/112, 7%), PRKDC (7/112, 6%), NOTCH4 (7/112, 6%), CCND3 (6/112, 5%), and FGF3/4/19 (6/112, 5%)." (PMID 37649078, 2023). "Therefore, NOTCH4 is a superior predictive biomarker in NRAS wildtype melanoma." (PMID 35967450, 2022). "We identified additional human tumor xenografts that expressed endothelial Notch4, including SEKI (melanoma) and DU145 (prostate cancer)." (PMID 38984877, 2024). "Our study further demonstrated the predictive role of NOTCH4 in melanoma immunotherapy and identified the benefit group as wildtype NRAS melanoma patients." (PMID 35967450, 2022). "In melanoma, HR was < 1 and the median OS of NOTCH4-MUT patients (median OS: 47.0 months) was longer than that of NOTCH4-WT patients (median OS: 42.0 months)." (PMID 34284787, 2021). "Anti-Notch4 antibody impaired VM in C8161 and SK-MEL-28 melanoma cells, and diminished clonogenicity in vitro by downregulating Nodal expression." (PMID 27034014, 2017).
melanoma (continued). "Interestingly, when we were writing our finding that the association between NOTCH4 mutation and ICI response was established, we found a study in which NOTCH4 predicted immune efficacy in pan-cancer, including NSCLC and melanoma." (PMID 35967450, 2022). "In NRAS mutant patients of the discovery cohort, NOTCH4-Mut melanoma had longer OS (mOS: 34.93 months vs. 6.43 months, HR = 0.37, 95% CI: 0.09–1.61, P = 0.17) than wildtype melanoma, but there was no statistical difference." (PMID 35967450, 2022). "However, there were no OS differences between NOTCH4-Mut and NOTCH4-Wt melanoma patients in the validation cohort." (PMID 35967450, 2022). "Importantly, Notch4 may induce suppression of Snail2 and Twist1 through downstream Hey1 and Hey2 targets and is non-canonically mediated in WM9 and WM164 melanoma cell lines." (PMID 37108670, 2023).
asthma (17 papers, 2012 to 2025). "Interestingly, targeting IL‐6R signalling can enhance the immunosuppressive properties of Tregs in association with inhibition of Notch4 expression, which may represent a therapeutic opportunity for patients with severe asthma." (PMID 40497455, 2025). "In asthma patients, upregulation of Notch4, Wnt, and Hippo in circulating Treg cells subvert them into Th2 and Th17 cells, diminishing Treg cell-mediated suppression and contributing to increase disease severity." (PMID 40430465, 2025). "In recent studies, we have identified Notch4 as the receptor on Tregs involved in these interactions, which is upregulated in circulating Tregs of asthma subjects in an IL‐6‐dependent manner." (PMID 40497455, 2025). "Targeting the IL-6R–STAT6 axis and Notch4 signaling has demonstrated preclinical efficacy in suppressing airway inflammation and remodeling in asthma models, with early clinical observations supporting IL-6R blockade in asthma patients." (PMID 40933988, 2025). "As a result, related studies have identified Notch4-mediated disruption of immune tolerance as a fundamental mechanism of tissue inflammation in asthma." (PMID 40443529, 2025). "NOTCH4 and its downstream effector pathways were upregulated on Treg cells of individuals with asthma and correlated with disease severity." (PMID 34785669, 2021). "Targets located in the MHC locus (NOTCH4 and ITPR3) were associated with 41 different phenotypes, including ulcerative colitis and multiple sclerosis signals in the opposite direction from asthma." (PMID 34103634, 2021). "Genome-wide association (GWA) studies on asthma have suggested that several polymorphisms in several genes, including ORMDL3-GSDMB, DENND1B, HLA-DP, SLC30A8, IL1RL1-IL18R1, IL33, SMAD3, TSLP, and NOTCH4 are associated with asthma." (PMID 23861779, 2013). "Further, NOTCH4 is highly expressed in the lung and may play a key role in the lung development and diseases such as asthma and lung arteriovenous shunts." (PMID 22952805, 2012). "Furthermore, Notch4 expression in Treg cells increases with asthma severity." (PMID 35387016, 2021). "In addition, Notch4 expression in the peripheral blood of murine asthma model stimulates regulatory T (Treg) cell destabilization and induces differentiation into Th2 and Th17 cells, via the Hippo pathway and Wnt axis, toward a Th17 and Th2 cell fate, respectively." (PMID 35387016, 2021). "The correlation of NOTCH4 gene polymorphism and asthma has not yet been reported." (PMID 31605414, 2020). "The discovery of a novel Notch4-Wnt-GDF15 axis in controlling allergic asthma in mice, and its subsequent validation in patients with severe asthma, undoubtedly offers new therapeutic prospects for restoring pulmonary immune tolerance and maintaining systemic balance." (PMID 40443529, 2025). "Notch4 disrupts Treg cells into TH2 and TH17 effector T (Teff) cells through Wnt and Hippo pathway-dependent mechanisms, thereby enhancing immune cell infiltration in the airways and exacerbating the inflammatory response in asthma." (PMID 40443529, 2025).
triple-negative breast carcinoma (15 papers, 2011 to 2025). An invasive breast carcinoma which is negative for expression of estrogen receptor (ER), progesterone receptor (PR), and human epidermal growth factor receptor 2 (HER2). "Bioinformatic analysis from human triple-negative breast cancer samples has identified endothelial Notch4 as a promising prognostic marker and highlighted its potential function in the tumor microenvironment." (PMID 38984877, 2024). "ALDH1 has been reported to play a role in promoting triple-negative breast cancer progression and enhanced drug resistance in a Notch receptor 4 (NOTCH4)-dependent manner." (PMID 35280765, 2022). "We have previously shown that Nicastrin regulates the EMT process and stem cell content in triple-negative breast cancers partially through Notch1/Notch4 activation." (PMID 24919951, 2014). "Here, we explored the Notch4 function in triple-negative breast cancer (TNBC)." (PMID 37149651, 2023). "Recently, a study by Speiser and collaborators showed increased Notch1 and Notch4 levels in tumor epithelial cells and vascular endothelial cells in triple-negative breast cancer samples, therefore highlighting the relevance of Notch4 expression in the vasculature." (PMID 23601498, 2013). "Furthermore, DTX3 acts as a tumor suppressor gene in triple-negative breast cancer and is expressed at a low level, which hinders its ubiquitination and degradation ability toward Notch4 and its ability to effectively inhibit triple-negative breast cancer metastasis." (PMID 34513839, 2021). "We examined the presence of Notch4 by IF staining of tumors derived from Calu-6 non–small cell lung carcinoma (NSCLC) and MDA-MB-231 triple-negative breast carcinoma implanted into BALB/c nude mice." (PMID 38984877, 2024). "Herein we have provided evidence of a novel therapeutic strategy to be exploited for the treatment of triple-negative breast cancer and potentially other breast cancer subtypes where PEA3 regulates Notch-1 and Notch-4." (PMID 21679465, 2011). "Our investigations are the first to show that PEA3 is a transcriptional activator of Notch-1 and Notch-4 in MDA-MB-231 breast cancer cells, an example of triple-negative breast cancer." (PMID 21679465, 2011). "PEA3 is a transcriptional activator of Notch-1 and Notch-4 and a repressor of Notch-2 in MDA-MB-231 cells, an example of triple-negative breast cancer cells." (PMID 21679465, 2011). "Thus we hypothesized that targeting of the PEA3 and/or Notch pathways might provide a new therapeutic strategy for triple-negative breast cancer as well as possibly other breast cancer subtypes where PEA3 regulates Notch-1 and/or Notch-4." (PMID 21679465, 2011).
COVID-19 (13 papers, 2021 to 2025). A disease caused by infection with severe acute respiratory syndrome coronavirus 2. "In humans, Notch4 triggers endothelial dysfunction in pre-eclampsia, and polymorphisms in Notch4 are associated with the severity of COVID-19–induced lung inflammation, thought to be mediated by endothelial activation." (PMID 38984877, 2024). "In COVID-19 patients, increased Notch4 expression on regulatory T cells is associated with disease severity and mortality, and its inhibition can rescue disease morbidity and mortality." (PMID 39595659, 2024). "A cohort of research on COVID-19 patients showed that expression of Notch4 was increased on Tregs and associated with disease severity, mortality, and recovery." (PMID 35874688, 2022). "Furthermore, the hub gene NOTCH4 has been implicated in both lung cancer and COVID-19." (PMID 39595659, 2024). "Whereas acute-COVID-19 severity and outcomes were previously correlated with Notch4 expression on Tregs, here, we show that Tregs in MIS-C were destabilized through a Notch1-dependent mechanism." (PMID 36282598, 2023). "Notch4 was similarly upregulated on circulating Tregs of pediatric patients with acute COVID-19, while both Notch4 and Notch1 were upregulated on those of patients with MIS-C." (PMID 36282598, 2023). "A range of studies consisting of COVID-19 patients showed that Notch4 expression was elevated on Tregs and correlated with illness severity, death, and healing." (PMID 36992283, 2023). "Circulating Tregs from adult patients with COVID-19 exhibit upregulated Notch receptor 4 (Notch4) expression, which increases with disease severity." (PMID 36594470, 2023). "Recent studies have outlined a prominent role for Notch4 in the immune dysregulation in acute COVID-19 and related respiratory viral illnesses." (PMID 36282598, 2023). "Whereas acute-COVID-19 severity and outcome were previously correlated with Notch4 expression on regulatory T (Treg) cells, here we show that the Treg cells in MIS-C are destabilized in association with increased Notch1 expression." (PMID 35441180, 2022). "In a prospective cohort of COVID-19 patients, the expression of Notch-4 in circulating Tregs increased, which suppressed the release of IL-18 induced AREG, thus restraining AREG-dependent tissue repair and promoting severe lung injury." (PMID 34631206, 2021). "Our previous studies have shown Notch4 to be specifically upregulated on circulating Tregs in adult patients with COVID-19; their origin could be traced to the lung in mouse models of viral infection." (PMID 36282598, 2023). "While Notch4 signaling on Tregs contributes to severe COVID-19 in adult patients, whether activation of Notch signaling pathways on Tregs promotes dysregulated immune responses during MIS-C is unclear." (PMID 36594470, 2023). "A prospective cohort study demonstrated that expression of Notch-4 is elevated in the circulating Tregs of COVID-19 patients, which can be used as an indicator of disease severity and may be associated with high mortality." (PMID 34631206, 2021). "A recent study has found that in COVID-19-induced ALI, Tregs express more Notch4, which is an inhibitor of tissue repair-related cytokines and proteins." (PMID 36646692, 2023). "Notch4 expression was also selectively increased on the circulating Tregs of adult and pediatric patients with severe COVID-19 or MIS-C but not on their Tconv cells." (PMID 36282598, 2023). "There was also no upregulation of Notch4 on Tregs of patients with mild COVID-19 or KD." (PMID 36282598, 2023).
gastric cancer (13 papers, 2016 to 2026). A primary or metastatic malignant neoplasm involving the stomach. "Notch 4 s’ high mRNA expression was also only associated with worsen OS in surgery alone gastric cancer patients, HR 2.12 (1.48–3.03), p = 2.7e-05." (PMID 27363496, 2016). "Notch 3 and Notch 4′s high mRNA expression is only associated with worsen OS in surgery alone for gastric cancer patients." (PMID 27363496, 2016). "It has also been shown that Notch4 promotes gastric cancer growth through activation of Wnt1/β-catenin signaling." (PMID 27435629, 2016). "In this report, we observed that Notch4′s high mRNA expression was also found to be significantly correlated to worsen OS for all gastric cancer patients, intestinal type cancer patients, and diffuse type of cancer patients." (PMID 27363496, 2016). "Notch4 activates Wnt1/β-catenin signaling to accelerate gastric cancer growth." (PMID 28881855, 2017). "miR181c may be a tumor suppressor by regulating the expression of target gene Notch4 in gastric cancer." (PMID 28881855, 2017). "In addition, Notch4 activation induced expression and activation of Wnt1, β-catenin and downstream target genes, c-Myc and cyclin D1, in gastric cancer cells, while Notch4 inhibition had opposite effects." (PMID 27363496, 2016). "Notch4′s high mRNA expression was also found to be significantly correlated to worsen OS for all gastric cancer patients, HR 1.98 (1.64–2.4), p = 9.3e-13, intestinal type cancer patients, HR 2.47 (1.77–3.64), p = 4.6e-08, and diffuse type cancer patients, HR 1.81 (1.18–2.76), p = 0.0054." (PMID 27363496, 2016). "Same as Notch3, the study about Notch4 in gastric cancer is also limited." (PMID 27363496, 2016). "In gastric cancer, we found CTHRC1 was highly co-expressed with many factors, such as ACVRL1, ANGPTL3, ANGPTL4, NOTCH4, VEGFB, VEGFC etc., which have been proved to play an important role in angiogenesis in various cancer." (PMID 35928443, 2022). "Transfection of pre-microRNA-181c inhibits proliferation of two types of gastric cancer cells (KATO-III and MKN45) by targeting the downstream oncogenic gene Notch4." (PMID 28881855, 2017). "Furthermore, studies have indicated that the activation of Notch1, Notch4, and DLL4 is crucial in the initiation and progression of gastric cancer." (PMID 35846998, 2022). "A recent gastric cancer study found that CADM2-AS1 is aberrantly expressed in cancer lymph node metastatic tissues, where it promotes metastasis through interaction with miR-5047 and activating NOTCH4 translation, indicating a biological process not directly linked to CADM2 per se." (PMID 41044382, 2026).
glioma (12 papers, 2013 to 2025). A benign or malignant brain and spinal cord tumor that arises from glial cells (astrocytes, oligodendrocytes, ependymal cells). "At the same time, based on the characteristics of over-expression of Notch4 (associated with the increase in the degree of tumor malignancy), it can be considered as the basis of classification for glioma." (PMID 35935338, 2022). "We additionally analyzed the expression of a panel genes (Angpt2, Sox4, Vegfa, Kdr, Itga1, Mcam, Notch4 and Ets1) associated with vascular abnormality in ECs using RNA extracted from total glioma tumor tissues from control and treated mice." (PMID 34867089, 2021). "For example, higher expression of Achaete-Scute Family BHLH Transcription Factor-1 (ASCL1), DLL1, Notch1, Notch3, Notch4, and Hey1 is associated with high-grade glioma and a worse prognosis." (PMID 36643842, 2021). "The Notch signaling pathway comprises four receptors: Notch1, which may function as either a tumor suppressor or oncogene; Notch2, considered a prognostic marker in glioma; Notch3, which promotes glioma cell proliferation; and Notch4, associated with increased tumor aggressiveness." (PMID 40942013, 2025). "Glioma cell / endothelial cell co-cultured aggregates displayed a greatly altered pattern of gene expression compared to glioma-only aggregates, with many of the genes putatively implicated in VM including NOTCH4, TGFβ, HGF and CD31 being significantly downregulated." (PMID 26203665, 2015). "The analysis shows that Notch1 and Sox2 have a positive feedback regulation mechanism, and Notch4 predicts the malignant degree of glioma." (PMID 35935338, 2022). "Notch4 is proposed as a less differentiated marker for glioma cells, and Notch4 expression increases from low-grade astrocytoma to high-graded GBM." (PMID 33381038, 2020). "Glioma-associated DEGs DOCK6, ILK, MGMT, NOTCH4 were up-regulated and FGF10, JAK1, JUNB, RHOB were down-regulated uniquely in the mouse." (PMID 29352201, 2018). "Other genes uniquely altered in mouse gliomas (e.g. NOTCH4, FGF10, JUNB, RHOB) may contribute further to murine-specific differences in glioma biology." (PMID 29352201, 2018). "The levels of proteins and mRNA in Notch1, Dll1, Notch4, Dll4, Hey1, Jagged1, CBF1, Hey2, and Hes1 in glioma cells are higher expression than those in healthy brain cells." (PMID 35935338, 2022). "Next, we demonstrated that transcript levels of NOTCH pathway members NOTCH1, NOTCH4, DLL1 and HES-1, which carry METTL3-dependent m6A peaks, were downregulated in METTL3-silenced glioma cells." (PMID 30781903, 2019). "Not much is known about the cooperation of Notch4 with other genes affecting glioma, and more studies are needed." (PMID 36643842, 2021). "This analysis revealed no major changes in NOTCH1, NOTCH2 and NOTCH4 transcript levels in our glioma population." (PMID 24143218, 2013).